PCNA (proliferating cell nuclear antigen)
Diseases named in the same sentence as PCNA in open-access papers (continued):
Sharing a sentence is not in itself a finding about the gene and the disease.
breast cancer (continued). "In breast cancer, CREB3L4 has been shown to bind to the promoter region of proliferating cell nuclear antigen (PCNA), with knockdown of CREB3L4 increasing cell apoptosis and cell cycle arrest." (PMID 41301006, 2025). "HBV infection lead to increased expression levels of several key genes in breast cancer cell lines, including CDK2, PCNA, CCNE2, CXCL8, E2F1, and CASP3." (PMID 40697521, 2025). "A novel small-molecule PCNA inhibitor, AOH1996, has shown great therapeutic potential in many cancers, including non-small cell lung cancer, colon cancer, and breast cancer." (PMID 41024256, 2025). "The PCNA mono-ubiquitination was also observed in two other human cell lines: MRC5sv, a human SV40-transformed lung fibroblast cell line, and the breast cancer MCF7 cell line." (PMID 39468223, 2025). "The immune regulatory roles of PCNA and TNF-α in breast cancer were further examined through immune correlation analyses of their skimmianine-associated hub proteins." (PMID 40430573, 2025). "Overall, skimmianine’s dual targeting of PCNA and TNF-α modulates the immune TME, highlighting its potential as a regulator of immune dynamics in breast cancer by simultaneously reversing immune suppression and mitigating tumor-promoting inflammation." (PMID 40430573, 2025). "In breast cancer (BC), M2 macrophages produced CCL17 that induced EMT gene (N-cadherin, vimentin and PCNA) expression in tumors via CCL17/CCR4/mTORC1 axis." (PMID 38794298, 2024). "In line with the MTT data and cell cycle analysis, the well-known genes that regulate cell proliferation and cell cycle progression, including Cyclin D1 and PCNA, were significantly downregulated when PNKY was knocked down in breast cancer cells." (PMID 37104007, 2023). "For instance, the expression patterns of conventional tumor markers, such as the proliferating cell nuclear antigen (PCNA) and the minichromosome maintenance protein 3 (MCM3) in breast cancer were found to be similar to those of KRT18." (PMID 36949761, 2023). "In pancreatic, colon, and breast cancer, HIF-1α was positively correlated with proliferating cell nuclear antigen." (PMID 36226248, 2022). "SNHG5 acts as a sponge for miR-154-5p, which normally suppresses proliferating cell nuclear antigen (PCNA), and therefore promotes cell cycle progression in breast cancer cells and inhibits apoptosis at the same time." (PMID 36139687, 2022). "We found that decreased expression of circ_6014 decreased the protein expression levels of PCNA, CDK2/CCNE1, and CDK4/6/CCND1, and overexpression of circ_6014 increased the expression of these proteins in breast cancer cells (Student’s t test, p < 0.05)." (PMID 35383130, 2022). "In SNHG5, overexpression increases the ability of breast cancer cells to proliferate and go through cell cycle, by releasing PCNA (proliferating cell nuclear antigen) from the inhibition of miR-154-5p." (PMID 32318335, 2020). "Interestingly, the Human Protein Atlas contains immunohistochemistry staining of the PCNA protein (antibody HPA030522) in normal breast tissue versus the overexpression in breast cancer ductal carcinoma implicating the abundance of the protein in breast cancer tissue as a potential biomarker." (PMID 27004791, 2016). "GCN5 knockdown decreased the protein levels of the proliferation marker proliferating cell nuclear antigen (PCNA) and amplified in breast cancer 1 (AIB1), but increased the protein levels of cell cycle inhibitor p21Cip1/Waf1 in HepG2 cells." (PMID 27486509, 2016).
breast cancer (continued). "ATAD2 colocalized with newly incorporated DNA (EdU) and the essential DNA replication protein PCNA at replication foci in MCF7 cells and in several other breast cancer cell lines (T47D, BT-549 and MDA-MB-231) independent of their hormone dependency." (PMID 27612420, 2016). "To determine the cellular proliferation in mammary tumors induced by LA7 cells, we analyzed the expression of the tumor markers PCNA and Ki67." (PMID 25996383, 2015). "The increased Tyr211 phosphorylation of PCNA induced by EGFR coincides with pronounced cell proliferation and is closely correlated with the poor survival of breast cancer patients." (PMID 25675097, 2015). "After estrogen treatment, however, the number of cells co-expressing both PCNA and CK18 was markedly increased, indicating estrogen stimulates proliferation of luminal epithelial lineage specific breast cancer progenitor or intermediate cells." (PMID 24558373, 2014). "One hundred and two breast cancer cases from I-SPY 1 were stained with anti-PCNA and anti-CD68 antibodies and the double positive PCNA+ TAMs enumerated." (PMID 24205370, 2013). "The results of this exploratory study indicate that high numbers of PCNA+ TAMs, in the absence of an anti-tumor immune microenvironment (as indicated by a low Tc/ClassII signature score), are associated with poor outcomes in breast cancer patients treated with neoadjuvant chemotherapy." (PMID 24205370, 2013). "In this study, we synthesized a TAT-based Y211F cell-penetrating PCNA peptide (CPPP) that blocks Y211 phosphorylation and inhibits growth of triple-negative and EGFR TKI-resistant breast cancer cells." (PMID 23593472, 2013). "In line with a significant decrease in PCNA, reduction expression of miR-150 significantly increased TUNEL-positive cells (apoptotic cells) in breast cancer xenografts." (PMID 24312495, 2013). "The results of this exploratory study indicate that high numbers of PCNA+ TAMs, particularly in the absence of an anti-tumor immune microenvironment (as indicated by a low Tc/ClassII signature score), are associated with poor outcomes in breast cancer patients treated with neoadjuvant chemotherapy." (PMID 24205370, 2013). "Therefore, targeting p-Y211 PCNA could also be an effective treatment strategy for breast cancer." (PMID 23593472, 2013). "We also found that high numbers of PCNA+ TAMs were associated with higher expression of MHC class II genes (data not shown), suggesting that these PCNA+ TAMs may be similar to the MHC class II high M1-like TAMs observed in the TS/A and 4T1 mouse mammary carcinoma models." (PMID 24205370, 2013). "We performed western blots to detect the expression of PCNA, Ki67 and c-Myc, in AAV2 infected breast cancer cell lines tested." (PMID 21827643, 2011). "This role is well documented in tumor cells, and particularly in breast cancer cells where E2F1 and its E2F1-target genes, including DHFR, PCNA and cyclin E, are overexpressed." (PMID 18431487, 2008). "Considering the comprehensive effects of PCNA and TNF-α described throughout this study as primary targets of skimmianine, their suppression underscores their relevance as actionable therapeutic nodes in breast cancer." (PMID 40430573, 2025). "In vivo cell experiment, we confirmed that HBV infection may lead to increased expression levels of several key genes in breast cancer cell lines, including CDK2, PCNA, CCNE2, CXCL8, E2F1, and CASP3." (PMID 40697521, 2025). "HBV infection may lead to increased expression levels of several key genes in breast cancer cell lines, including CDK2, PCNA, CCNE2, CXCL8, E2F1, and CASP3." (PMID 40697521, 2025). "Astragaloside IV-mediated upregulation of TRHDE-AS1 was shown to be correlated with the decreased expression of key protein markers of tumour growth and metastasis like Proliferating Cell Nuclear Antigen (PCNA), MMP9 and MMP7, ameliorating breast cancer proliferation and migration." (PMID 40176927, 2024).
breast cancer (continued). "In the control group, the induction of mammary cancer by DMBA resulted in about 30% luminal A, 10% luminal B, 60% HER2-enriched and no cases of triple-negative tumors (TNBC), classified solely on the base of the levels of expression of ER, PR, HER2 and PCNA." (PMID 39610845, 2024). "Exposure of human breast cancer cell lines to an exercise-conditioned medium obtained from contracted myotubules, with or without doxorubicin, reveals a reduction in PCNA expression and a synergistic relationship with the anticancer drug." (PMID 36612320, 2023). "Also, EGCG arrested the G1 phase of the breast cancer cell cycle by lowering the expression of cyclin D, cyclin E, CDK 4, CDK 1, and proliferating cell nuclear antigen (PCNA)." (PMID 34072700, 2021). "Previously, decreased H3K4me3 by AKT inhibitor MK2206 in PIK3CA-mutated TNBC cells was shown to be associated with the suppressed expression of aurora kinase B (AURKB), proliferating cell nuclear antigen (PCNA) and other genes that are critical to breast cancer survival." (PMID 33664847, 2021). "Furthermore, nuclear S6K2 correlated with staining of proliferation markers such as Ki-67 and proliferating cell nuclear antigen (PCNA), suggesting a role for nuclear S6K2 in breast cancer cell proliferation." (PMID 32054043, 2020). "Notably, a strong positive correlation between the expression of PCNA and COX2 in breast cancer has been recently highlighted, also in accordance with our previous findings." (PMID 33218180, 2020). "Besides, ectopic expression of EYA2 promoted proliferation of breast cancer cells accompanied with the up-regulation of EGFR, cyclin E, and PCNA." (PMID 30761270, 2019). "Since lower concentrations of NO reduced proliferation of AA breast cancer cell lines, we further examined its effect on Mn SOD and Cu/Zn SOD as well as on various proliferation (cyclin D1 and PCNA), apoptosis (Bax and Bcl2), and oxidative stress (NOX4) markers." (PMID 27473585, 2016). "In fact, PCNA, TOP2A and other genes in the patterns have been targets for breast cancer therapy." (PMID 27004791, 2016). "Additionally, based on the detection of EDU and PCNA, A1CF (-8aa) promotes cell proliferation via upregulating the expression of IL-6 in basal-like breast cancer cells (MAD-MB-231)." (PMID 27231908, 2016). "For these analyses we focused only on the more aggressive ER+ subtype luminal B that most frequently metastasizes and the ER- basal breast cancer patients, where mammaprint and PCNA metagene failed to predict poor outcome." (PMID 26020648, 2015). "Four known biomarkers (CHEK2 in both plasma and urine, CDKN1B, PCNA, and THBS1) were identified as false positives (red) in our breast cancer list, and seven (KRAS, GDNF in both breastmilk and plasma, MYCL1 in both blood and serum, CD40LG, CGA, CTAG1A, ERCC6, and HRAS) in our lung cancer list." (PMID 25379168, 2014). "Moreover, presence of S6K2 in the nucleus positively correlated with proliferating cell nuclear antigen (PCNA) and Ki-67 staining in breast cancer tissues, demonstrating a link between the presence of S6K2 in this compartment and cell proliferation." (PMID 23898460, 2013). "Investigating the expression of both cell regulatory proteins (cyclin D1 and PCNA) demonstrated that there were significant decreases in both PCNA and cyclin D1 expression as a result of RAGE siRNA knockdown in all of the investigated breast cancer cell lines." (PMID 23579957, 2013). "We observed a reduction in the levels of PCNA protein upon the silencing of NONO in breast cancer cells, indicating a disruption in DNA replication and supporting an idea that p21 may be involved in mediating this effect." (PMID 37370134, 2023). "Additionally, their expression was positively correlated with that of Ki-67, PCNA and MCM2, which was consistent with the predictions of CancerSEA, implying that RACGAP1 and KPNA2 could facilitate breast cancer progression." (PMID 36200070, 2022).
breast cancer (continued). "The SYK inhibitor, BI 1002494, caused no increase in proliferation in breast cancer cells or primary mammary epithelial cells in 2D or 3D cultures, nor changes in proliferation (CD1/2, CDK4, PCNA, Ki67) or invadopodia markers (MMP14, PARP, phospho-vimentin Ser56)." (PMID 32292575, 2020). "Similarly, the up-regulation of PCNA, CHECK1 or GZMB might be related to other aspects of apoptosis or breast cancer pathways." (PMID 31825969, 2019). "Immunohistochemical analysis of the tumor regions revealed low intensity p85 and PCNA expression in p42-AV or two of p42-CTD-AV (183–394 and 280–394 aa) injection groups compared with control vector group, suggesting that p42 and its CTD inhibits breast cancer growth in vivo." (PMID 27464702, 2016). "Compared with cancer tissue sheets of EMT-6 alone, PCNA proliferation index analysis and TUNEL assay showed that TCs and other breast stromal cells facilitated the formation of typical nest structure, promoted the proliferation of breast cancer cells, and inhibited their apoptosis." (PMID 23206234, 2013). "No formal study of PCNA gene regulation has been demonstrated in breast cancer cells." (PMID 18949048, 2008). "Furthermore, γ-TmT and individual tocopherols were administered to Sprague-Dawley rats which were induced with NMU carcinogen; treatment with γ-TmT, γ-, and δ-tocopherol decreased PCNA levels while increased the levels of cleaved-caspase 3 in mammary tumors, whereas α-tocopherol was not active." (PMID 22254089, 2011). "Upon 16-day treatment with BI01002494 no specific increase in proliferation (cyclin D1/2, PCNA) or invadopodia (MMP14, PARP) markers is observed in either DU4475 or MDA-MB-468 breast cancer cell lines." (PMID 32292575, 2020). "With the exception of two neoadjuvantly treated mammary carcinomas, PLA showed moderate to strong Rad18/PCNA colocalization signals in all cases (including some IGF1R/PCNA negative cases)." (PMID 32701997, 2020). "Modulating HTRA2 expression in CCR2-H SUM225, CCR2-KO and parental DCIS.com cells led to changes in spheroid size and PCNA expression, indicating that HTRA2 exerts important effects on breast cancer cell growth regardless of cell line or CCR2 status." (PMID 31208996, 2019). "Among the 147 prognostic gene pairs found in breast cancer, only a single gene pair IGKV1-5_MCM2 contains a meta-PCNA gene (MCM2) and no other prognostic gene pairs contain a meta-PCNA gene." (PMID 31856825, 2019). "Altering ALDH1A1 expression in CCR2-H SUM225, CCR2-KO and parental DCIS.com cells led to changes in spheroid size and PCNA expression, indicating that an important role for ALDH1A1 in breast cancer cell growth regardless of cell line or CCR2 status." (PMID 31208996, 2019). "As with MCF-10A cells co-cultured with fibroblast from normal mammary tissue adjacent to ER(-) primary breast cancers, both DBP and DEHP (10 and 100 nM) significantly decreased PCNA expression, while BBP and E2 did not have any effect on PCNA expression." (PMID 29940022, 2018). "In terms of biologic results, our data show that the breast cancer cell lines (MDA-MD-231 and Cal-51) harbored less Dnmt1/PCNA interactions and less 5-methycytosine (5 mC) than non-tumor breast cells (MCF10A)." (PMID 21470401, 2011). "However, GluOC had no obvious effect on the PCNA and cyclin D1 protein levels in MCF7 breast cancer cells." (PMID 35413833, 2022). "Further in line with this, while ER- tumors are more proliferative than ER+ tumors, as measured by the expression levels of the S phase-specific proliferation marker PCNA, EEF1A1 mRNA-low tumors are more proliferative than EEF1A1 mRNA-high tumors in ER+ but not in ER- breast cancers." (PMID 30224719, 2018). "First, we observed that breast cancer cell lines express different protein levels of CENP-I, but these differences do not markedly change when their levels are compensated for by the protein levels of the proliferation marker PCNA (data not shown)." (PMID 28977935, 2017).
breast cancer (continued). "Although there is a significant correlation between PCNA and TK1 staining of breast cancer tissue, TK1 showed a significant correlation with stage and grade while PCNA did not, indicating that TK1 might be a more accurate marker for diagnosis and prognosis." (PMID 22778736, 2012).
glioma (94 papers, 2010 to 2026). A benign or malignant brain and spinal cord tumor that arises from glial cells (astrocytes, oligodendrocytes, ependymal cells). "One recent study also found that PCNA is strongly associated with the stemness and radio‐resistance in glioma tumor cells." (PMID 33459509, 2021). "Since GCN5 expression was associated with PCNA expression in glioma tissues, we performed a serum starvation and releasing model to detect GCN5 expression during cell cycle progression." (PMID 26378521, 2015). "All in all, our above results showed that GCN5 was upregulated in human glioma tissues and was associated with PCNA and MMP9 expression." (PMID 26378521, 2015). "Collectively, all our data identified the disruption of the Dnmt1/PCNA/UHRF1 interactions as a molecular event associated with the degree of global DNA hypomethylation in glial/glioma cells." (PMID 20613874, 2010). "In the present article, we report that Akt overexpression and diuron exposure promote the glioma formation from neural progenitor cells via the induction of DNA hypomethylation mediated by two distinct pathways: the loss of DNMT1/PCNA/UHRF1 interactions and the APOBEC3γ overexpression." (PMID 31727122, 2019). "In addition, IHC assay revealed that DACT2 overexpression upregulated the expression of Bax and downexpressed the expression of YAP, PCNA and CyclinD1 and in glioma tissues, and DACT2 knockdown caused opposide result." (PMID 28796248, 2017). "We then examined the relationship between GirLncSig and cell proliferation and found that in the glioma samples from the TCGA database, the expression of almost all model-related sub-risk lncRNAs was positively correlated with the expression of cell proliferation markers Ki67 and PCNA." (PMID 37547724, 2023). "Thus, we conclude that the loss of DNMT1/UHRF1/PCNA and the APOBEC3γ overexpression are the two leading molecular causes of the global DNA hypomethylation seen in cells at the origin of Akt + diuron-induced glioma." (PMID 31727122, 2019). "Since it was found that NUAK2 modulated glioma proliferation by inhibiting p27kip1, we detected the expression pattern of PCNA (a general marker of dividing cells) to determine the relationship between NUAK2 and the proliferation of SCs." (PMID 39071701, 2024). "CREB, a potential effector of CART, regulates cell proliferation by modulation of cyclin B, D and proliferating cell nuclear antigen (PCNA) expression in glioma cells." (PMID 37373130, 2023). "The reality is that, in clinical work, we can assess the proliferation of gliomas by KI67 or PCNA, but we cannot make a better quantitative assessment of glioma infiltration." (PMID 37091145, 2023). "In the nude mice model, maslinic acid can inhibit the growth of glioma and inhibit the expression of the proliferation protein PCNA." (PMID 35799612, 2022). "In conclusion, glioma cells require RAD18 for the bypass of the TMZ-induced DNA lesion O6MeG by a mechanism that involves the ubiquitination of PCNA and the activation of the TMZ-induced DDR." (PMID 35365623, 2022). "Among the positively correlated genes, evidence shows that GNG5, HMGB2, PCNA and HSPB11 can induce the proliferation and metastasis of glioma, causing poor prognosis and reducing the OS of patients with glioma." (PMID 34953037, 2022). "Another study reports that silencing FOXD1 represses MEK-2, ERK-1, Bcl-2, DAF, and PCNA expression levels and increases Bax expression, thus repressing glioma cells’ proliferation and metastasis." (PMID 34937497, 2022). "This further facilitates immune escape of glioma cells by increasing the tumor burden and expression of PCNA and Ki67, prominent nuclear markers to demonstrate proliferative phase of the cell cycle, and decreasing the CD8+ T cell population in glioma." (PMID 36338993, 2022). "Tissue microarrays and immunohistochemistry were used to detect FKBP10, Hsp47, p-AKT (Ser473), p-CREB (Ser133) and PCNA expression in glioma tissues and xenografts." (PMID 33557829, 2021).